EGFR (epidermal growth factor receptor)
Diseases named in the same sentence as EGFR in open-access papers (continued):
Sharing a sentence is not in itself a finding about the gene and the disease.
cancer (continued). "Accumulating evidence shows that NCOA3 is highly expressed in a various human cancers, and it can interact with nuclear receptors and other transcription factors to regulate the expression of their target genes involved in many signaling pathways, including EGFR, Akt, MAPK, E2F1, and Notch." (PMID 29360267, 2018). "Besides the plethora of biological processes evoked by prostanoids through the binding to their receptors, PGE2 reportedly interacts with various receptor tyrosine kinase (RTK) in a process termed transactivation, exemplified by EGFR activation in several cancer cell types." (PMID 29599917, 2018). "Because crosstalk between the signaling pathways controlled by these receptors has emerged as a mechanism of both cancer progression and resistance to therapy, dual inhibition of these targets may lead to improved outcomes for patients with MET- and EGFR-driven cancers." (PMID 29926131, 2018). "Moreover, recent findings have shown that EGFR signaling can provide a critical adaptive survival mechanism that allows cancer cells to evade kinase fusion specific inhibitors, providing a rationale to co-target EGFR in order to reduce risks of developing drug resistance." (PMID 29455670, 2018). "Thus, combining CD44v6 and EGFR targeting may increase overall sensitivity for the detection of poorly differentiated carcinomas." (PMID 29992954, 2018). "Hence, production of EpEX by carcinoma cells could locally impact the regulation of EGFR-dependent proliferation and EMT." (PMID 30261040, 2018). "Moreover, anti-EGFR antibody therapy uses extensive in treatment cancer." (PMID 28430586, 2017). "Interestingly, treatment of various cancer cell lines with the photosensitizer Photofrin (porfimer sodium, log P = 8.5) alone downregulated EGFR protein expression, which was enhanced upon PDT, indicating that Photofrin alone is able to downmodulate EGFR expression." (PMID 27803950, 2017). "It is not clear what role EINCR1 might have in the tumourigenic process but as EINCR1 is a target of the EGF pathway and EGFR-regulated pathways are often activated in cancer cells it appears likely that it might be an important mediator of dysregulated signalling." (PMID 28732076, 2017). "Likewise, the EGFR down-regulated group (n = 229) was chosen based on whether the average expression level of EGFR signaling down-regulation-responsive genes in cancer samples was ≧1.5X lower than that of normal samples." (PMID 28537886, 2017). "The cytotoxic rules may be applicable for other cancer cells expressing EGFR." (PMID 28588218, 2017). "In addition to its single agent activity, it has also been shown that this tyrosine kinase inhibitor acts in synergy with standard chemotherapy such as Fluorouracil in various cancer patients and we were able to pair Fluorouracil with the EGFR gene as well (rank 3)." (PMID 28427468, 2017). "Analysis of the mechanisms modulating EGFR signaling and resistance to EGFR-targeted inhibitors has provided insights into the specific inhibition of EGFR signaling activity, e.g., by TKIs and mAbs, and has permitted further exploration of the development of drug-resistant cancers." (PMID 29140271, 2017). "In the context of human cancers where the BIM deletion allele predicts poorer therapeutic responses and clinical outcomes, such as in CML or EGFR-NSCLC, the splice-switching ASOs we have identified may be used in combination with appropriate TKIs to overcome the negative effects of the BIM deletion." (PMID 29100409, 2017). "Thus, EMab-134 could be useful in various experiments and advantageous for the pathological identification of EGFR in many cancers." (PMID 29090976, 2017). "ISLR/Meflin is a newly discovered surface and secreted pluripotency-related protein whose over-expression has been described in cancer stroma and fibrotic diseases, and a recent immunoprecipitation study has demonstrated its interaction with receptor tyrosine kinases (RTKs) such as EGFR and PDGFRA." (PMID 28415643, 2017).
cancer (continued). "Hence, EMab-51 could be useful in all present experiments and will likely be an advantageous tool for the pathological identification of EGFR in many cancers." (PMID 28891752, 2017). "Therefore, it is possible alcohol regulates cancer stemness by activating EGFR and ErbB2." (PMID 29156633, 2017). "In addition to IL-6, STAT3 can be activated by EGFR in many cancer types." (PMID 29262529, 2017). "Moreover, EGFR-stimulated cancer growth depends on SCD1 activity." (PMID 28724430, 2017). "Indeed, other studies also suggest that the cellular location of the EGFR not only can influence response to therapeutics but could also play an important role in cancer progression and patients’ survival." (PMID 28032593, 2017). "Furthermore, DMA_21mCG comprising cancer cell receptor (EGFR)-binding affibody peptides (DMA_21mCG (aff+)) was successfully endocytosed by EGFR-expressing cancer cells (A431) without causing any cytotoxicity." (PMID 29229979, 2017). "Contrary, deletion of the EGFR specifically in hepatocytes has been shown to lead to enhanced development of liver cancer in mice, demonstrating that this receptor may have beneficial properties in the protection against cancer." (PMID 28970798, 2017). "The pro-inflammatory cytokine IL-8 has been previously shown to induce increased cancer stem cell renewal, cell invasion and metastasis and epithelial to mesenchymal transition, and we now show a novel mechanism that that links high NO levels to EGFR-dependent IL-8 induction in BL2 cells." (PMID 29113326, 2017). "In particular, SW48 and LIM1215 cancer cells, that are wild type (WT) for KRAS, BRAF, NRAS and PIK3CA genes, and GEO cancer cells, that have a KRAS codon 12 mutation, are sensitive to the anti-epidermal growth factor receptor (EGFR) monoclonal antibody cetuximab." (PMID 28978118, 2017). "However, how EGFR regulates MUFA synthesis in cancer remains elusive." (PMID 28724430, 2017). "Exosomes containing EGFR-VII, EGFR, PDPN and IDH1 secreted by spongioblastoma were isolated, which confirmed that detection of circulating exosomes could predict efficacy of clinical drugs and cancer mutations." (PMID 28851367, 2017). "However, Nrf2 activation-induced EPGN upregulation and subsequent EGFR activation might actually be pro-tumorigenic and act counter to its anti-cancer effects." (PMID 27635238, 2016). "Recent work has also highlighted a co-localization between Src with EGFR, particularly within lipid rafts of cancer cells, Moreover, it was reported that Src could phosphorylate EGFR, and mediate EGFR signaling in various cancer cell lines." (PMID 26830684, 2016). "EGFR, a cell surface receptor with intrinsic protein kinase activity, has been recognized as a key player in vascular biology and, development and progression of cancer due to its diverse signaling responses to regulate cellular proliferation, differentiation, migration and survival." (PMID 27287039, 2016). "As it has been reported that EGFR stability plays a role in the survival of EGFR driven cancers, we hypothesized that differential TKI-induced receptor degradation between the sensitive L858R and delE746-A750 and the resistant T790M may also play a role in drug responsiveness." (PMID 27612423, 2016). "However, cancer cells may circumvent the drug effects of EGFR inhibitors by activating alternative pathways, thus limiting the efficacy of such therapeutic approaches." (PMID 27705911, 2016). "Thus, EGFR signaling can be an attractive target for cancer treatment." (PMID 26863567, 2016). "Therefore miR-217-CAGE feedback loop may offer valuable target for overcoming resistance to various anti-cancer drugs such as taxol, EGFR inhibitor and HER2 inhibitor." (PMID 26863629, 2016).
cancer (continued). "Firstly, EGFR-expressing cancer cells will be efficiently targeted and lysed by EGFR-CAR NK cells, while oHSV-1 still has a chance to eradicate the remaining EGFR-negative or EGFR-dim cancer cells that may exist or are derived from EGFR-positive cells due to tumor antigen loss." (PMID 27050072, 2016). "Both cancer growth and dissemination are activated by numerous extracellular activators including neuropeptides and factors released by shedding from the plasma membrane which depends on matrix metalloproteases (MMPs) such as Epidermal Growth Factor Receptor (EGFR) ligands." (PMID 27834811, 2016). "However, we found a somatic mutation in EGFR (p.D587H, hg19 chr7:55233009G > C) that had never been observed in any public cancer genome sequencing databases (at the time of this report)." (PMID 27245685, 2016). "However, cancer patients that have benefited from costly EGFR TKI therapy quickly generate resistance to the drug with 70% known and 30% unknown reasons." (PMID 27376254, 2016). "TKI resistance can arise through aberrant activation of the PI3K/AKT/mTOR axis in several cancer types, including NSCLC, often through PTEN deletion or activating PIK3CA mutations; however, such mechanisms were elucidated primarily in the context of EGFR inhibitors." (PMID 27472392, 2016). "In particular, notable advances have been made in cancer therapy for example, with the discovery of Herceptin to treat breast cancer patients with HER2 amplification, and with Iressa for the treatment of non-small cell lung cancer patients with an EGFR mutation." (PMID 27438146, 2016). "Thus, the interaction of drug and EGFR may be responsible for the over-activation of EGFR signalling pathways in cancers." (PMID 27249340, 2016). "Therefore, the modulation of EGFR by miR-218-5p may explain why the downregulation of miR-218-5p during NSCLC carcinogenesis can promote cancer progression." (PMID 27057632, 2016). "Therefore, we hypothesize that AP-2alpha is a common mechanism for feedback from EGFR inhibition in for all human cancers that are sensitive to EGFR inhibitors." (PMID 27650546, 2016). "Among these compounds, compound H20 exhibited the most potent antiproliferative activity against four cancer cell line variants (A549, MCF-7, HeLa, HepG2) with IC50 values of 0.46, 0.29, 0.15 and 0.21 μM respectively, which showed the most potent EGFR inhibition activities (IC50 = 0.08 μM for EGFR)." (PMID 27527130, 2016). "Importantly, studies carried out with a new class of anti-cancer agents (i.e., Disulfide bond Disrupting Agents [DDAs]), which target epidermal growth factor receptor (EGFR) and its family members HER2 and HER3, show that DDAs disrupt CDCP1 ternary signaling complexes." (PMID 27495374, 2016). "As mAbs and EGFR-TKIs target distinct molecular domains of the EGFR, we hypothesized that the combination of these two classes of EGFR inhibitors could be a potential therapeutic strategy for the treatment of EGFR-expressing cancers." (PMID 27655662, 2016). "Thus targeting of this immune regulatory mechanism may additionally contribute to the therapeutic successes of EGFR-targeting treatments in cancer patients." (PMID 26881744, 2016). "However, there have been limited information on humoral immune response to EGFR in cancer." (PMID 27833557, 2016). "Hence, combination of miR-30a-5p and other EGFR-TKIs may increase the cancer cell sensitivity to targeted drugs and provide a novel approach for NSCLC treatment." (PMID 27895663, 2016). "In addition, it has been shown that epidermal growth factor receptor (EGFR) signaling may be required for cancer self-renewal." (PMID 26757880, 2016).
cancer (continued). "Although ligand-independent dimerization was reported in cancer or transfected cells with large amounts of receptor, protein over-expression might lead to the formation of aggregates, and artificial formation of dimeric EGFR." (PMID 26943906, 2016). "Blocking this AREG/EREG-induced activation of EGFR might promote cancer cell death." (PMID 27344184, 2016). "Since several human cancers have elevated expression of EGFR along with Eph receptors, therapeutic agents targeted against Eph family members could potentially also affect tumors through EGFR inhibition." (PMID 27941840, 2016). "Hence, miR-30a-5p may play vital roles in overcoming the acquired resistance to EGFR-TKIs, and provide useful information for establishing novel cancer treatment." (PMID 27895663, 2016). "This may be due to the constitutively high level of EGFR in cancers cells such as A431 or SK-CO15." (PMID 26918609, 2016). "However, EGFR activation was not positively associated with cancer cell viability in response to paclitaxel in R182 cells." (PMID 27708225, 2016). "In order to test whether compound 968 sensitized cancer cells to other anticancer drugs except erlotinib, gefitinib (the first selective inhibitor of EGFR) and cispatin (the first member of a class of platinum-containing anti-cancer drugs) were used for the evaluation." (PMID 26575584, 2016). "Thus, CAS 879127-07-8 could be used as a seed to develop a novel anti-cancer drug that simultaneously inhibits two unrelated proteins, EGFR and microtubules." (PMID 27117592, 2016). "Moreover, both CTSS and EGFR hold potential as therapeutic targets for cancer treatment." (PMID 27387133, 2016). "Thus, understanding the molecular mechanisms affecting cancer cell sensitivity or resistance to anti-EGFR inhibitors may be of help in deciding on treatment options, and in new translational studies." (PMID 30370422, 2016). "However, resistance to the anti-EGFR therapy in variety of cancer types have suggested ingenious utilization of the potential antistress mechanism/s by cancer cells to overcome effects of the anti-EGFR therapies for inhibiting cancer cell survival and growth." (PMID 30370422, 2016). "Therefore, investigating and understanding of the EGFR upstream modulatory mechanisms might provide some novel targets for cancer therapy." (PMID 26918608, 2016). "Among patients with stage IV disease, treatment with erlotinib was associated with Hispanic and API heritages, not smoking, having an adenocarcinoma, having an EGFR mutation, living at least two months after cancer diagnosis and being treated at a larger hospital." (PMID 27294665, 2016). "Also, TNBC can be classified as basal type cancer defined by EGFR and cytokeratin 5/6 staining." (PMID 26757880, 2016). "Progesterone-receptor membrane component 1 (PGRMC1/Sigma-2 receptor) is a haem-containing protein that interacts with epidermal growth factor receptor (EGFR) and cytochromes P450 to regulate cancer proliferation and chemoresistance; its structural basis remains unknown." (PMID 26988023, 2016). "Indeed, the LGI network suggests the recognition by FimH-LD of the EGFR from carcinoma cells." (PMID 27406561, 2016). "To further demonstrate the reliability of MDP, we found a statistical significant association between the EGFR inhibitor Gefitinib (Iressa) (p-value = 0.03) and the tyrosine kinase inhibitor Selumetinib (p-value = 0.03) with somatic missense EGFR mutations in CCLE cancer cell lines." (PMID 26513174, 2015).
cancer (continued). "Cancer cells with low expression of ERCC1 have a decreased ability to repair DNA damage, an increase in the number of EGFR mutations and increased sensitivity to platinum-based chemotherapy, which may be why patients with NSCLC with EGFR mutations have a higher response rate to chemotherapy." (PMID 25667646, 2015). "Additionally, our study proposes that EGFR tyrosine kinase inhibitors-resistant cancer cell lines express specific inflammatory cytokines and angiogenesis signals to promote vascularization and perhaps autocrine immunity stimulation as important strategy to combat cancer treatment." (PMID 25948104, 2015). "In addition, MKP101 effectively inhibited vascular endothelial growth factor-induced endothelial proliferation, tube formation, migration of human umbilical vein endothelial cells and proliferation of HCC827, an epidermal growth factor receptor-addicted cancer cell line." (PMID 26401847, 2015). "These pro-apoptotic and anti-proliferative mechanisms may be attributable to a combination of direct inhibition of cancer cell growth by interfering with the EGFR autocrine pathway and the secondary anti-angiogenic effects of VEGFR-2 blockade in endothelial cells." (PMID 26574153, 2015). "In addition, the EGFR plays a critical role in cancer cell migration and invasion." (PMID 26503469, 2015). "Therefore, altered EGFR signaling is pivotal for cancer cell growth, invasion, and metastasis." (PMID 26515726, 2015). "Thus, anEGFR-SOX2-BCL2L1 pathway may be implicated in cancer cells with wild-type EGFR,whereas the EGFR-FOXO6-SOX2-BIM/BMF pathway we describe is specific for cells thatare dependent on mutant EGFR signals for their survival." (PMID 25686219, 2015). "Thus, considerable attention has been given to targeting the EGFR pathway for anti-cancer therapy." (PMID 25674792, 2015). "Thus, TM treatment, through the potentiation of p38 activation, may trigger EGFR internalization and/or degradation, which in turn may sensitize drug-resistant cancer cells to chemotherapy such as cisplatin." (PMID 26568478, 2015). "Therefore, manipulation of versican expression with relevant EGFR signaling alteration may provide novel therapeutic mechanism against EMT process in cancer." (PMID 26515726, 2015). "Therefore, EGFR has become a key target for cancer gene therapy." (PMID 25435943, 2015). "We found that ibrutinib exhibited selective anti-proliferation activity against EGFR primary mutants (L858R, del19)-expressing cancer cells but moderately active against drug induced secondary gate-keeper T790M mutation and not active against wt EGFR-expressing cells." (PMID 26375053, 2015). "Thus, in this study, we aimed to evaluate whether targeting the EGFR tyrosine kinase may have a therapeutic effect against EC, by accurately assessing the expression levels of EGFR in cancer cells." (PMID 26673416, 2015). "Therefore, we examined whether Amiodarone regulates the migratory and invasive phenotypes of cancer cells through EGFR pathways similar to that found in our previous work with zebrafish embryos (submitted to Cardiovascular Research)." (PMID 26515726, 2015). "Therefore, EGFR and its downstream signaling components can be used as major targets in developing novel agents for cancer treatment, such as chimeric monoclonal antibodies (cetuximab and panitumumab) and tyrosine kinase inhibitors (TKIs) (gefitinib, erlotinib, and afatinib)." (PMID 26273639, 2015). "Finally, our findings will provide a rationale to develop a new class of drug to disrupt asymmetric dimerization, which would be potent to treat a subset of cancer patients harboring dimerization-dependent oncogenic EGFR mutants including C-terminal deletion mutants." (PMID 25826094, 2015). "Therefore, our results demonstrate that besides the canonical role of EGFR as a receptor tyrosine, the mitochondrial translocation of EGFR may enhance cancer invasion and metastasis through regulating mitochondria dynamics." (PMID 26497368, 2015).